EMP2 (epithelial membrane protein 2)
Diseases named in the same sentence as EMP2 in open-access papers (continued):
Sharing a sentence is not in itself a finding about the gene and the disease.
malignant glioma (1 paper, 2022). A grade III or grade IV glioma arising from the central nervous system. "In malignant glioma samples, the proportion of high EMP2 expression is significantly higher than in low-grade glioma." (PMID 36217151, 2022). "Also, EMP2 can promote abnormal angiogenesis of malignant glioma by regulating the expression of VEGF-A and angiogenesis-related STAT3 cell signaling pathway." (PMID 36217151, 2022).
meningioma (1 paper, 2021). A generally slow growing tumor attached to the dura mater. "Through sample analysis of meningioma patients, it can be found that the expression of EMP2 mRNA is much higher in meningioma patients than in non-meningioma patients, making it as a potential marker for further screening and diagnosis of meningioma." (PMID 33673851, 2021).
metastatic disease (1 paper, 2013). "We thus hypothesized that imaging of EMP2 may serve as an early monitor of response to tailored therapy or be useful prior to surgical resection to identify metastatic disease." (PMID 22585360, 2013).
Miscarriage (1 paper, 2023). A pregnancy that ends at a stage in which the fetus is incapable of surviving on its own, defined as the spontaneous loss of a fetus before the 22th week of pregnancy. "In addition, another study showed that genetic defects in epithelial membrane protein 2 (EMP2) can inhibit angiogenesis and oxidative phosphorylation by suppressing FAK and Src to inhibit the production of HIF-1α in the trophectoderm, leading to miscarriage." (PMID 37355665, 2023).
nasopharynx cancer (1 paper, 2019). "Ectopic expression of EMP2 in nasopharynx cancer cells in vitro impairs cell growth, enhances the efficiency of radiotherapy, induces cell cycle arrest at S phase, and increases apoptosis at both early and late stages." (PMID 31652725, 2019). "EMP2 protein is expressed at low levels or is undetectable in most high-grade tumors (grades III and IV) in nasopharynx cancer." (PMID 31652725, 2019). "The clinical outcome of nasopharynx cancer is significantly worse for patients who do not detectably express EMP2." (PMID 31652725, 2019).
upper tract urothelial carcinoma (1 paper, 2015). "High EMP2 immunointensity was recognized as a prognostic indicator for patients with upper tract urothelial carcinoma (UTUC), possibly via suppression of cell proliferation." (PMID 25940704, 2015).
urothelial carcinoma (1 paper, 2021). A malignant neoplasm derived from the transitional epithelium of the urinary tract (urinary bladder, ureter, urethra, or renal pelvis). "In urothelial carcinoma of the upper urinary tract, EMP2 interacts with integrins αV and β3 to regulate cell adhesion and migration." (PMID 33799364, 2021).
tumor (26 papers, 2010 to 2025). "The reduced level of LC3B indicated a decrease in tumor autophagy levels associated with the decrease in EMP2 expression, which is consistent with the in vitro results." (PMID 39866225, 2025). "Upon intravenous administration, EMP2-directed ADCs circulate, reach tumor sites, and bind to tumor-associated antigens." (PMID 41173824, 2025). "It has been shown that tumor expression of epithelial membrane protein 2, EMP2 is associated with aggressive disease in EC, and that EMP2 represents a novel biomarker for EC development." (PMID 31783595, 2019). "A member of the growth arrest specifϊc-3/peripheral myelin protein-22 (GAS3/PMP22) family of tetraspan proteins, overexpression of EMP2 is associated with tumor progression as well as poor patient survival." (PMID 22585360, 2013). "However, while we can show an increase in the number of strongly EMP2-positive tumor cells, we cannot show causation between treatment and antigen expression." (PMID 38672563, 2024). "Accumulating evidence suggests that EMP2 is a promising and intriguing molecular target in various malignancies, potentially improving tumor control and survival." (PMID 39866225, 2025). "The results revealed a significant reduction in these markers in the shEMP2 group compared to the control group, indicating a substantial downregulation of EMP2 in the experimental group’s tumor tissues." (PMID 39866225, 2025). "Overall, these results indicated that FK002-exatecan significantly induced cell cycle arrest and increased apoptosis in EMP2-overexpressing tumor cells by targeting EMP2." (PMID 41173824, 2025). "Mechanistically, FK002-exatecan specifically bound to EMP2 and was internalized into tumor cells, followed by intracellular trafficking to the lysosome and exatecan release, which induced cell cycle arrest and apoptosis." (PMID 41173824, 2025). "Analysis of the TCGA RNA-seq data revealed significant differences in EMP2 expression levels across various tumor tissues." (PMID 39866225, 2025). "Compared to the control group, the EMP2 knockdown group exhibited a significant decrease in tumor growth rate, size, and wet weight." (PMID 39866225, 2025). "Following 21 days of inoculation, the mice were euthanized, and the intact tumor tissues were embedded and sectioned for immune-histochemical staining of Ki67, EMP2, ITGA5, and LC3B." (PMID 39866225, 2025). "Through target identification, we determined that FK002Ab specifically targeted the human EMP2 protein on the surface of tumor cells." (PMID 41173824, 2025). "In contrast, EMP2 demonstrated significantly higher expression in the Tumor group, with an average Log2 (TPM + 1) of 4.516 ± 0.803 compared to 4.165 ± 0.411 in the Normal group (p < 0.001)." (PMID 39866225, 2025). "Among the 18 tumor types with paired normal and tumor samples, EMP2 mRNA expression was significantly higher in BRCA, THCA, ESCA and HCC compared to their respective normal tissues." (PMID 39866225, 2025). "The results demonstrated that EMP2 expression levels were significantly higher in the Tumor group compared to the Normal group." (PMID 39866225, 2025). "We found FK002-exatecan specifically kills tumor cells with high EMP2 expression in a dose-dependent manner." (PMID 41173824, 2025). "EMP2 promotes tumor invasion, appears to regulate tumor-mediated neoangiogenesis, and has been shown to increase the proportion of cancer stem-like cells." (PMID 38672563, 2024). "In contrast, treatment with the anti-EMP2 mAbs significantly reduced the number and intensity of EMP2-positive tumor cells, suggesting the specificity of the mAb treatment." (PMID 38672563, 2024). "While we have previously shown that anti-EMP2 treatment can reduce the tumor initiation frequency, its effects on taxane-resistant cells remain unexplored." (PMID 38672563, 2024). "Our results strongly suggest a correlation between docetaxel treatment and EMP2 tumor expression, whereby docetaxel increases EMP2 levels." (PMID 38672563, 2024).
tumor (continued). "The correlation between EMP2 upregulation, taxane resistance, and poor overall survival, coupled with the promising results of anti-EMP2 mAbs in reducing tumor burden, underscore the potential of targeting EMP2 to manage taxane-resistant TNBC." (PMID 38672563, 2024). "In the concurrent model, anti-EMP2 mAbs significantly reduced the average tumor volume and post-euthanasia tumor weight compared to those treated with docetaxel and a control mAb." (PMID 38672563, 2024). "When we stratified the data based on the inclusion of a taxane into the treatment protocol, a significant increase in EMP2 expression resulted compared to the tumor pre-treatment group." (PMID 38672563, 2024). "Our findings indicate that high EMP2 levels correlate with poor patient survival outcomes, and we demonstrate a link between taxane treatment and a subsequent increase in EMP2-positive tumor cells." (PMID 38672563, 2024). "In contrast, treatment with docetaxel and anti-EMP2 mAbs significantly reduced the relative mean EMP2 expression within the tumor parenchyma." (PMID 38672563, 2024). "Our syngeneic models revealed that the number and/or intensity of EMP2-positive tumor cells increased following taxane treatment." (PMID 38672563, 2024). "While the increase in expression observed did not correlate with patients’ stage, age, menopausal status, or ethnicity, the increase in EMP2-positive tumor cells following neoadjuvant therapy significantly correlated with tumor recurrence (p = 0.04)." (PMID 38672563, 2024). "Treatment with docetaxel and the control IgG significantly increased the number of strongly EMP2-positive tumor cells observed." (PMID 38672563, 2024). "Of note, EMP2 expression, as evaluated by immunohistochemical staining, is largely restricted to the tumor parenchyma, whereas the tumor stroma (endothelial cells, immune cells) show below-detection levels of expression." (PMID 38672563, 2024). "A significant reduction in tumor weight was observed in the combination treatment group with the anti-EMP2 mAb compared to the saline and control IgG-treated groups." (PMID 38672563, 2024). "As EMP2 has been shown to promote tumor initiation and be a potential marker for stemness, we initially queried levels of its transcript using ROC plotter and Kaplan–Meier (KM) plotter." (PMID 38672563, 2024). "As EMP2 expression can be heterogeneous within the naïve tumor parenchyma, it is possible that strongly EMP2-positive cells are more resistant to taxane treatment, thus leaving the tumor mostly populated with “high-EMP2” cells after taxane treatment." (PMID 38672563, 2024). "Within the docetaxel plus control IgG-treated group, both the number and intensity of EMP2-positive tumor cells appeared to increase." (PMID 38672563, 2024). "Crucially, our study reveals that anti-EMP2 monoclonal antibodies (mAbs) can act in synergy with taxane-based chemotherapy, reducing tumor load in both syngeneic and xenograft models of TNBC." (PMID 38672563, 2024). "In cancer-related studies, we observed that the higher the expression level of EMP2 in various tumor models in vitro, the more obvious the expression of pathological angiogenesis-related pathways was." (PMID 37421595, 2023). "The regulation of gene expression and specific signal pathways of EMP2 in different tumor cells must be further studied to develop more effective tumor diagnosis and treatment methods." (PMID 36217151, 2022). "Existing research has suggested that EMP2 can regulate tumor cell proliferation, apoptosis, and metastasis and has vast potential for use in diagnosing and treating some gynecological tumors." (PMID 36217151, 2022). "In NSCLC, EMP1 was associated with clinical resistance of gefitinib, EMP2 gene silencing resulted in activation of ERK and JNK in NSCLC cells, and EMP3 expression was significantly lower in tumor tissues compared to healthy lung tissues." (PMID 33799364, 2021).
tumor (continued). "Currently, the tumor biological role of EMP2 and its impact on miRNA expression, particularly exosomal miRNA expression, in NSCLC cells is not yet understood." (PMID 33799364, 2021). "Based on our data, considering that both p-p38 and p-ERK1/2 are two key components of the MAPK pathway, we conclude that EMP2 suppressed tumor cell growth mainly by inhibition of MAPK pathway in NSCLC." (PMID 33799364, 2021). "Overexpression of EMP2 suppressed tumor cell growth, migration, and invasion, resulting in a G1 cell cycle arrest, with knockdown of EMP2 leading to enhanced cell migration, related to MAPK pathway alterations and disruption of cell cycle regulatory genes." (PMID 33799364, 2021). "Exosomes isolated from transfected cells were taken up by tumor cells, carrying EMP2-downregulated microRNAs (miRNAs) which participated in regulation of the tumor microenvironment." (PMID 33799364, 2021). "In this study, increased levels of EMP2 were observed in clinical tumor samples after bevacizumab treatment in both unpaired and paired analyses." (PMID 33063013, 2020). "EMP2 H-scores were significantly higher in recurrent tumor samples after bevacizumab treatment (mean H-score 2.31 vs 1.76; P = .006)." (PMID 33063013, 2020). "Clinical characteristics and survival data from these patients were collected, and tumor samples were stained for EMP2 expression." (PMID 33063013, 2020). "EMP2 H-scores were significantly higher in recurrent tumor samples after bevacizumab treatment relative to paired initial tumor samples (mean difference 0.571; P = .019)." (PMID 33063013, 2020). "A heat map was created from RNA expression values by histological identifier and there was increased EMP2 RNA expression in areas of microvascular proliferation and hyperplastic blood vessels relative to other areas of the tumor." (PMID 33063013, 2020). "EMP2 has been previously linked to angiogenesis through both VEGF-dependent and VEGF-independent pathways in multiple tumor models." (PMID 31508419, 2019). "The inoculation of GBM cells overexpressing EMP2 into nude mice accelerates tumor formation, mainly through the growing vasculature of intracranial tumors." (PMID 31652725, 2019). "EMP2 protein expression inversely correlates with the histologic grades of uroepithelial cancer cells, and overexpression of EMP2 impairs cancer cell proliferation and inhibits tumor development." (PMID 31652725, 2019). "Among the eight upregulated genes observed for cell adhesion, migration, and invasion, we detected three genes positively regulating cell adhesion and affecting tumor dissemination (Ptpn14, Myl12b, and Emp2)." (PMID 29108266, 2017). "Of 14 candidate transcripts, only downregulation of EMP2 significantly predicts inferior overall survival, suggesting that EMP2 plays a potential tumor suppressor role in UBUC." (PMID 25940704, 2015). "The most upregulated gene in the tumor cell fractions (i.e., with the lowest p value) was epithelial membrane protein 2 (EMP2, p = 5.49E-36)." (PMID 26299617, 2015). "In human tumor cell lines, the antibody binding induced EMP2 internalization and degradation, prompting the need for a residualizing imaging strategy." (PMID 22585360, 2013). "Localized treatment with the anti-EMP2 diabody showed therapeutic efficacy with reduced tumor load in xenograft models for endometrial and ovarian tumors." (PMID 22585360, 2013). "EMP2 physically associates with and regulates the activity of integrin-FAK signaling complexes, with the consequence that high levels of EMP2 increase tumor cell invasion." (PMID 22585360, 2013). "Injections with radiometal-labeled anti-CD20 minibody showed low levels of tracer within the tumor, suggesting that the high radio-uptake of labeled EMP2 minibody was specific." (PMID 22585360, 2013). "We have previously shown that the KS83 diabody recognizes both murine and human EMP2 and has therapeutic potential as seen in a number of tumor models." (PMID 22585360, 2013).
tumor (continued). "After 20 h, HEC1A/EMP2 tumors showed a 1.7-fold increase in 64Cu-DOTA-KS83 minibody localization compared with the wild-type tumor (p < 0.01) and a 5.4-fold increase in localization compared with Ramos tumors (P < 0.001)." (PMID 22585360, 2013). "EMP2 expression demonstrates significant tissue specificity and heterogeneity in various human tissues and tumor tissues, where it may play a role in either promoting or inhibiting tumor growth." (PMID 39866225, 2025). "Interestingly, the role of EMP2 varies among different tumors, exhibiting either oncogenic or tumor-suppressing expression." (PMID 39866225, 2025). "EMP2, a protein that spans the cell membrane four times, is crucial for binding various cell surface molecules and facilitates transmembrane transport of materials, influencing cell adhesion and migration—key processes in the metastatic cascade of tumor cells." (PMID 39866225, 2025). "In this manner, we speculate that targeting EMP2 may reduce the pool of viable cancer stem-like cells, thereby leading to a reduction in overall tumor burden." (PMID 38672563, 2024). "Similarly, in the sequential model, two initial treatments with docetaxel followed by the addition of anti-EMP2 mAb significantly reduced the average tumor volume compared to treatment with the control mAbs." (PMID 38672563, 2024). "Moreover, we show that targeting EMP2 in combination with docetaxel reduces tumor load in syngeneic and xenograft models of TNBC." (PMID 38672563, 2024). "Both the bi-weekly anti-EMP2 therapy and weekly docetaxel administration reduced tumor load." (PMID 38672563, 2024). "The differential expression of EMP2 in various tumor tissues plays different roles." (PMID 36217151, 2022). "In this study, we combined EMP2, exosomes, and miRNA into one research frame to investigate the functional role of EMP2, its influence on the expression of exosomal miRNAs, and the effects of EMP2-derived exosomes on tumor cell migratory behavior." (PMID 33799364, 2021). "EMP2 might further affect the tumor microenvironment by regulating tumor microenvironment-associated miRNAs." (PMID 33799364, 2021). "Additionally, only a handful of tumor pathways were investigated, given the functional diversity of EMP2 in human cancers." (PMID 33799364, 2021). "The data above collectively suggested that EMP2 may help regulate neoangiogenesis within the tumor parenchyma as well as tumor cell invasion along the leading edge." (PMID 33063013, 2020). "EMP2 also functions as a tumor suppressor in urothelial carcinoma." (PMID 31652725, 2019). "On the other hand, an antibody directed against Epithelial membrane protein-2 (EMP2) (a protein involved in tumor migration and neoangiogenesis) reduces tumor formation and growth in ALDH1+ cells and indirectly downregulates ALDH1 expression although the precise mechanism of action is not clear." (PMID 31752447, 2019). "The down-regulation of miR-101-3p induced by NEAT1 over-expression could enhance the mRNA and protein expression levels of EMP2 and then act as a tumor suppressor in NPC." (PMID 29050268, 2017). "The mouse xenograft model was also used to evaluate whether knockdown of EMP2 and double knockdown of CREB1 and EMP2 affected tumor growth in vivo." (PMID 25940704, 2015). "We predict that with further refinement anti-EMP2 antibody fragments may be have value for imaging of tumor localization and therapeutic response in patients with EMP2-positive malignancies." (PMID 22585360, 2013). "Given that EMP2 overexpression plays an important role in aggressive tumor behavior and poor clinical outcome, early stage detection and quantification of EMP2 may be clinically relevant and used for selection of optimal therapy for individual patients." (PMID 22585360, 2013). "Indeed, PET images of tumor bearing mice injected with 64Cu-DOTA-KS83 minibody produced excellent radioactive uptake in EMP2-positive tumors." (PMID 22585360, 2013).